GALP (galanin like peptide)
Description:
[Isoform 1]: Hypothalamic neuropeptide which binds to the G-protein-coupled galanin receptors (GALR1, GALR2 and GALR3). Involved in a large number of putative physiological functions in CNS homeostatic processes, including the regulation of gonadotropin-releasing hormone secretion. [Isoform 2]: Exhibits potent and dose-dependent vasoconstrictor and anti-edema activity in the cutaneous microvasculature, a physiologic effects which does not appear to be mediated via GALR1 or GALR2. Exhibits antimicrobial activity against Gram-negative bacterias, inducing bacterial membrane blebbing.
Synonyms: GAL
Tractability: Antibody: UniProt places it where antibodies can reach, with medium confidence; UniProt predicts a signal peptide or a membrane-spanning region; its Gene Ontology location is reachable by antibodies, with medium confidence.
Gene: Protein-coding gene on chromosome 19 (56,176,008 to 56,185,775, forward strand). Ensembl gene ENSG00000197487.
Subcellular location: Secreted
Gene Ontology:
Molecular function: protein binding; hormone activity
Biological process: behavioral response to starvation; response to hormone; response to insulin; signal transduction
Cellular component: extracellular region
Genetic constraint (gnomAD): Loss-of-function variants: 10 observed, 10.26 expected, observed/expected ratio (o/e) 0.97, 90% interval 0.6 to 1.62. The upper end of that interval is the gene's LOEUF score, 1.62, which puts it in group 6 of 6, group 1 being the genes least tolerant of losing a copy. Missense variants: 125 observed, 119.05 expected, observed/expected ratio (o/e) 1.05, 90% interval 0.91 to 1.22. Synonymous variants: 47 observed, 46.32 expected, observed/expected ratio (o/e) 1.01, 90% interval 0.8 to 1.29.
Homologues: Orthologues: chimpanzee GALP (98% identical), dog GALP (65% identical), mouse Galp (64% identical), rat Galp (62% identical), pig GALP (55% identical).
Diseases named in the same sentence as GALP in open-access papers:
GALP is named in the same sentence as 19 diseases in open-access papers, as found by Europe PMC text mining. Sharing a sentence is not in itself a finding about the gene and the disease. The quoted sentences say what the papers report.
Obesity (6 papers, 2016 to 2023). Accumulation of substantial excess body fat. "Increased expression of the Lyve1 gene associated with GALP administration may indicate restoration of lymphatic function that has been impaired by obesity." (PMID 37958806, 2023). "Intracerebroventricular administration of GALP has anti-obesity effects in obese mouse models and reduces food intake and body weight in wild-type mice." (PMID 37958806, 2023). "Our research group intends to further analyze the detailed mechanism of the anti-obesity effect of intranasal administration of GALP and conduct experiments for future clinical application to humans." (PMID 37958806, 2023). "The anti-obesity effects of GALP have been established at both the central and peripheral levels, with promising clinical implications." (PMID 37958806, 2023). "We therefore conducted a comprehensive investigation into the anti-obesity potential of GALP through intranasal administration." (PMID 37958806, 2023). "We used whole-genome DNA microarray and metabolomics analyses to determine the anti-obesity effects of intranasal GALP in DIO mice fed an HFD." (PMID 37958806, 2023). "Experiments in obese mice have also demonstrated the anti-obesity effects of GALP, as continuous intracerebroventricular administration to ob/ob mice for 14 days results in a sustained decrease in food intake and body weight." (PMID 37958806, 2023). "Recent studies have revealed that intranasally applied galanin-like peptide (GALP), which is an endogenous ligand of GALRs, has a central anti-obesity action in addition to its role in food intake regulation." (PMID 34859381, 2021). "Thus, the anti-obesity effects of GALP result from improvements in peripheral tissue lipid metabolism via the sympathetic nervous system." (PMID 37958806, 2023). "The aim of this research was to test the efficacy and potential clinical application of intranasal administration of galanin-like peptide (GALP) as an anti-obesity treatment under the hypothesis that GALP prevents obesity in mice fed a high-fat diet (HFD)." (PMID 37958806, 2023). "No alterations in locomotor activity or taste aversion were observed, suggesting that the anti-obesity effect of GALP may be due to increased energy metabolism." (PMID 37958806, 2023). "Taken together, these findings suggest that the anti-obesity effects of GALP may occur through feeding inhibition as well as through improvement of hepatic lipid metabolism." (PMID 37958806, 2023). "The anti-obesity effects of GALP may be due to the sympathetic nervous system-mediated suppression of appetite in peripheral tissues together with inhibition of fatty acid β-oxidation and fatty acid synthesis." (PMID 37958806, 2023). "The anti-obesity effect of GALP may be due to an increase in energy metabolism, although the detailed mechanism has not yet been elucidated." (PMID 37958806, 2023). "We hypothesized that intranasal administration would be the preferred method for translating the anti-obesity effects of GALP into clinical applications." (PMID 37958806, 2023). "Particularly, newly discovered galanin-like peptide (GALP) may play a role in boosting appetite, body weight, and obesity." (PMID 29132311, 2017). "Galanin-like peptide (GALP) has an anti-obesity effect in rats and mice." (PMID 27323911, 2016). "GALP may serve as a therapeutic option in the prevention and cure of obesity and dyslipidemia in clinical practice in the future." (PMID 26892462, 2016). "These newly observed physiological functions are exerted via actions on the SNS and via FGF-21-mediated humoral control, and may explain the previously reported anti-obesity effects of GALP." (PMID 26892462, 2016). "Furthermore, an anti-obesity effect of GALP after intranasal administration was shown." (PMID 34859381, 2021). "It is thought that one of the anti-obesity effects of GALP could take place via this mechanism." (PMID 26892462, 2016).
Obesity (continued). "Intranasally administered GALP also decreased food intake, water intake, body weight and locomotor activity in DIO mice, another model of obesity." (PMID 27323911, 2016). "This, coupled with the fact that the actions of GALP were not fully inhibited by guanethidine, suggests that further studies are required to elucidate how GALP exerts its anti-obesity effects." (PMID 26892462, 2016).
breast carcinoma (3 papers, 2020 to 2021). "These analyses also allow us to identify features that help stratify difficult to treat breast cancer subtypes, i.e., GALP, IYD, and PARP12 were all significantly associated with survival in non-senior triple-negative breast cancer patients." (PMID 32241256, 2020). "Higher expression of STXBP5, GALP, and LOC387646 indicated an unfavorable prognosis for breast cancer (BC) patients." (PMID 34947885, 2021). "Establishing a LASSO-generated molecular gene signature revealed that the increased expression of genes STXBP5, GALP and LOC387646 indicate a poor prognosis for a breast cancer patient." (PMID 32241256, 2020).
alcoholism (1 paper, 2022). "Dysregulation of galanin, GALP and alarin has been implicated in various neuroendocrine conditions such as nociception, Alzheimer’s disease, seizures, eating disorders, alcoholism, diabetes, and spinal cord conditions." (PMID 36561569, 2022).
Glucose intolerance (1 paper, 2025). Glucose intolerance (GI) can be defined as dysglycemia that comprises both prediabetes and diabetes. "Animal studies have demonstrated that GALP deficiency exacerbates high-fat diet-induced glucose intolerance, and the observed reduction in GALP levels in obese PCOS patients may promote chronic inflammation and lipid metabolism dysregulation, collectively driving GDM development." (PMID 40458174, 2025).
glucose metabolism disorders (1 paper, 2025). "Additionally, GALP enhances insulin sensitivity in adipose tissue and skeletal muscle, and its downregulation may contribute to glucose metabolism disorders, thereby increasing GDM susceptibility." (PMID 40458174, 2025).
Insulin resistance (1 paper, 2016). Increased resistance towards insulin, that is, diminished effectiveness of insulin in reducing blood glucose levels. "It is therefore possible that intranasally administered GALP aggravates insulin resistance, or that it promotes gluconeogenesis in the liver." (PMID 27323911, 2016).
liver cancer (1 paper, 2025). An epithelial or non-epithelial malignant neoplasm that arises from the liver. "Moreover, anti-apoptotic and anti-proliferative effects of galanin and GALP were shown to be mediated through GalR2, which can explain no liver cancer development in mice under the CEL treatment." (PMID 39968178, 2025).
Salmonella Infections (1 paper, 2023). Infections with bacteria of the genus SALMONELLA. "GALP administration induces S. aureus infection (mmu05150) and Salmonella infection (mmu05132) pathways, while the antimicrobial peptide defensin expression is highly suppressed." (PMID 37958806, 2023).
sarcoma (1 paper, 2023). A usually aggressive malignant neoplasm of the soft tissue or bone. "EWSR1-WT1-regulated genes expressed more highly in recurrent than primary DSRCT included GJB2, GAL, and GALP, which were recently identified as highly enriched in DSRCT compared to other sarcoma types." (PMID 37457440, 2023).
cancer (2 papers, 2022 to 2024). A tumor composed of atypical neoplastic, often pleomorphic cells that invade other tissues. "Immunohistochemistry results indicated significantly elevated GALP, CACNA1C, COL16A1, PENK, C4BPA, PSMA2, and CXCL9 expression in cancer tissues." (PMID 38481252, 2024). "Immunohistochemistry results indicated significant upregulation of GALP, CACNA1C, COL16A1, PENK, C4BPA, PSMA2, and CXCL9 in cancer tissues." (PMID 38481252, 2024).
GALP also shares sentences with these, for which no sentence is quoted: Alzheimer disease (1 paper); diabetes (1); dyslipidemia (1); eating disorder (1); gestational diabetes mellitus (1); metabolic disease (1); polycystic ovary syndrome (1); triple-negative breast carcinoma (1); tumor (1).